VIM (vimentin)
Diseases named in the same sentence as VIM in open-access papers (continued):
Sharing a sentence is not in itself a finding about the gene and the disease.
pulmonary sarcoidosis (5 papers, 2018 to 2025). Sarcoidosis affecting the lung parenchyma. "The authors demonstrated the formation of IgM to vimentin in the peripheral blood in groups with pulmonary and extrapulmonary sarcoidosis, and IgG to vimentin in patients with pulmonary sarcoidosis." (PMID 39598118, 2024). "In our cohort, IgM anti-vimentin antibodies was higher in both pulmonary-only and extra-pulmonary sarcoidosis compared to normal controls and higher in pulmonary-only compared to extra-pulmonary sarcoidosis cohort." (PMID 36264970, 2022).
retinal degeneration (5 papers, 2011 to 2023). Degeneration of the retina. "GFAP expression in Müller cells is an indicator of tissue stress, and it has been associated with retinal degeneration, whereas the intermediate filament protein vimentin is ubiquitously expressed in the Müller cells of many mammalian species." (PMID 26733810, 2015). "As gliosis involves macroglia, we investigated their gliotic response to determine the role of S100β and intermediate filaments (IFs) GFAP, vimentin, and nestin during tissue repair in a laser-induced model of retinal degeneration." (PMID 37298126, 2023). "Evaluation of regions associated with overt retinal degeneration and RPE phenotypic changes showed decreased detection of the mitochondrial marker COX-IV after PGC-1 deletion, whereas the EMT markers—collagen-VI, vimentin, TWIST1, and ZEB1- were increased." (PMID 31101737, 2019). "In order to investigate if the data from the mouse model correspond to the characteristics of retinal degeneration in patients, three human retina samples containing drusen and three samples without drusen were stained with the selected gliotic markers (vimentin, nestin, GFAP, and S100β)." (PMID 37298126, 2023). "Previous studies have shown that during retinal degeneration, the Müller cells present a marked modification in protein expression, beginning to express filament protein such as GFAP and also vimentin that may change the structure density of the cells." (PMID 21901134, 2011).
retinal detachment (5 papers, 2011 to 2024). An eye emergency condition which may lead to blindness if left untreated. "Vimentin has been implicated in photoreceptor degeneration following retinal detachment in mice." (PMID 39768141, 2024). "The retinal astrocytes and Müller glial cells exhibit similar responses to injury, such as hypertrophy, upregulation of GFAP, vimentin, and GS, as observed in rat models of retinal detachment and retinitis pigmentosa." (PMID 28381236, 2017). "The amount of the Eno1, vimentin, albumin and prohibitin was increased, while the amount of tubulin β‐2C, fructose‐bisphosphate aldolase A and other proteins was reduced in the retina of animals after retinal detachment." (PMID 28781956, 2017). "Beta-tubulin, vimentin, and glial fibrillary acidic protein (GFAP) may structurally reinforce the endfeet region of Müller cells and are upregulated throughout this cell type following retinal detachment and other forms of injury." (PMID 22065916, 2011).
thymoma (5 papers, 2007 to 2022). A neoplasm arising from the epithelial cells of the thymus. "A mixture of less represented CTLA-4+/Vimentin+ tumor cells as well as a more represented CTLA-4+/Vimentin− tumor cells was observed in AB thymoma sections." (PMID 29682176, 2018). "Finally, in AB thymomas the expression of vimentin and CTLA-4 in tumor cells was evaluated using an anti-human vimentin and anti-CTLA-4 mAbs." (PMID 29682176, 2018). "In regard to AB thymomas, a mixture of less represented mesenchymal CTLA-4+/Vimentin+ tumor cells as well as a more represented CTLA-4+/Vimentin− tumor cells was observed in AB thymoma sections." (PMID 29682176, 2018). "Surprisingly, we observed in type A and type AB thymomas a large number of CD20+, EMA+, vimentin+ fibroblast-like elongate neoplastic epithelial cells." (PMID 17498299, 2007). "On the contrary, B2 thymoma cells are vimentin-negative; therefore, stromal cells are present in the NF primary culture even if a subset of cytokeratin-positive cancer cells is still present." (PMID 35681572, 2022). "The expression of vimentin has been described in epithelial cells of type A and AB thymomas, but the absence of pan cytokeratins excluded the presence of epithelial cancer cells in the AMt primary culture." (PMID 35681572, 2022). "In type A thymoma, neoplastic epithelial cells stained strongly for EMA, CK7, vimentin, and CD20." (PMID 17498299, 2007). "The type A component in AB thymomas showed an immunophenotype virtually indistinguishable from the one of type A neoplasms, including the strong expression of vimentin." (PMID 17498299, 2007). "The thymoma-derived primary thymic cells expressed cytokeratin, a marker of epithelial cells, with a mean of 79% positive cells except for cells derived from the thymic carcinoma 2637 that were negative for cytokeratin but expressed vimentin." (PMID 30897085, 2019). "No CD20+, vimentin+ neoplastic epithelial cells were seen in type B thymomas." (PMID 17498299, 2007). "In type B1 thymomas, neoplastic epithelial cells showed expression of EMA and CK7 at the stromal interface, and were consistently CD20, CK20, CD5, and vimentin negative." (PMID 17498299, 2007).
thyroid (5 papers, 2014 to 2023). "N-cadherin (encoded by CDH2) and vimentin (encoded by VIM) were identified to promote thyroid tumorigenesis." (PMID 32033410, 2020). "A set of EMT markers (E-cadherin, vimentin, α-SMA, and fibronectin) were evaluated in thyroid tissues from AITD patients and controls through RT-qPCR, immunohistochemistry (IHC), and western blot (WB)." (PMID 36834770, 2023). "Although in later studies these changes were not considered to be indicative of a specific thyroid pathologic condition, we found an increase in vimentin expression levels in AITD patients." (PMID 36834770, 2023).
transitional cell carcinoma (5 papers, 2009 to 2022). A malignant neoplasm arising from the transitional epithelium, usually affecting the urinary bladder, ureter, or renal pelvis. "Expression of vimentin was found in 69% cases of transitional cell carcinoma and its expression is associated with the grade of transitional cell carcinoma." (PMID 32650368, 2020). "The aim of study was to assess the expression profile of cytokeratin and vimentin in Transitional Cell Carcinoma and its association with clinical outcome such as sex, age, and grade of the tumour via immunohistochemistry." (PMID 26640315, 2015). "Significant differences were noticed in expression pattern of CK and vimentin in inflammatory lesion and Transitional Cell Carcinoma cases." (PMID 26640315, 2015). "Transitional Cell Carcinoma (TCC) cases were examined for both markers; most of the cases showed both CK and vimentin positivity and our results showed that cytokeratin and vimentin have pivotal role in development and progression of TCC." (PMID 26640315, 2015). "Immunohistochemically, the giant cell sarcomatoid element was positive for various kinds of cytokeratins and vimentin while the squamous and transitional cell carcinoma elements were positive for various kinds of cytokeratins and negative for vimentin." (PMID 20062688, 2009).
undifferentiated carcinoma (5 papers, 2008 to 2025). A usually aggressive malignant epithelial neoplasm composed of atypical cells which do not display evidence of glandular, squamous, or transitional cell differentiation. "Some Pbrm1-deleted PDAC cells exhibited a transient state of degradation of the tubular component to a component of undifferentiated carcinoma with high vimentin expression and loss of expression of PBRM1 and CK19." (PMID 40454484, 2025). "Twist expressions were negative for both mucinous and undifferentiated carcinoma lesions, whereas Snail and Vimentin expressions were positive in undifferentiated carcinoma lesions." (PMID 40427213, 2025).
urothelial carcinoma of the bladder (5 papers, 2020 to 2024). "Regarding vimentin staining, the expression of vimentin in bladder urothelial carcinomas was significantly associated with adverse prognostic indicators such as progression and recurrence." (PMID 39451592, 2024). "Our study demonstrates that the sensitivity and specificity of TWIST1/Vimentin promoter methylation in urine samples for differentiating bladder urothelial carcinoma (BUC) from benign diseases and healthy controls reached 78% and 83%, respectively." (PMID 38575639, 2024). "Specifically, we aim to analyze the EMT in bladder urothelial carcinomas using E-cadherin and vimentin as markers." (PMID 39451592, 2024). "Our findings reveal that hypermethylation of the TWIST1/Vimentin promoter occurs in bladder urothelial carcinoma, and its high sensitivity and specificity suggest its potential as a screening and therapeutic biomarker for urothelial carcinoma of the bladder." (PMID 38575639, 2024). "In this study, we show that vaccination against extracellular vimentin (eVim) with the CVx1 vaccine extends the lifespan of dogs with urothelial carcinoma of the bladder that are treated with COX-2 inhibition, as compared to historical controls treated with carboplatin and a COX-2 inhibitor." (PMID 37568772, 2023). "Moreover, the expression level of key EMT-related proteins such as N-Cad, MMP9, Vimentin, Slug and Snail were correspondingly decreased, which indicated us that the up-regulated CDCA3 could participate in the EMT process of bladder urothelial carcinoma." (PMID 33980246, 2021).
adenoid cystic carcinoma (4 papers, 2013 to 2020). A malignant tumor arising from the epithelial cells. "In addition, perinuclear dot-like vimentin expression is characteristic of BSCC, in contrast to the diffuse cytoplasmic expression of adenoid cystic carcinoma." (PMID 23833636, 2013). "Adenoid cystic carcinoma is positive for smooth muscle actin, whereas BSCC is negative; the latter has also greater reactivity for vimentin compared to BSCC." (PMID 29221167, 2017).
ameloblastoma (4 papers, 2008 to 2026). The most common odontogenic tumor, arising from the epithelial component of the embryonic tooth and usually affecting the molar-ramus region of the mandible or maxilla. "Indeed, double staining revealed the presence of many βIII-Tubulin+/Vimentin− cells in close contact with the ameloblastoma epithelium (white arrowheads), thus supporting a neuronal, non-mesenchymal identity for the observed βIII-Tubulin+ cells." (PMID 32155948, 2020). "Blood vessels could be detected within the Vimentin+ stroma as well as in close proximity to the Vimentin− ameloblastoma epithelium." (PMID 32155948, 2020). "Immunocytochemistry revealed that the cultured ameloblastoma cells expressed normal levels of cytokeratins 14 and 16 and only weakly expressed cytokeratin 18 and vimentin, indicating that these cultures were primarily comprised of ameloblastoma cells of epithelial origin." (PMID 18588710, 2008). "Primary cultures of ameloblastoma cells expressed cytokeratin (CK) 14 and 16, and MMP-2, but only weakly expressed CK18 and vimentin." (PMID 18588710, 2008).
amyotrophic lateral sclerosis (4 papers, 2016 to 2025). Amyotrophic lateral sclerosis (ALS) is a neurodegenerative disease characterized by progressive muscular paralysis reflecting degeneration of motor neurons in the primary motor cortex, corticospinal tracts, brainstem and spinal cord. "In other neurodegenerative disorders, such as amyotrophic lateral sclerosis (ALS), co-localization of TDP-43 (a hallmark pathological protein in ALS) and vimentin was observed in dermal fibroblasts through immunophenotyping." (PMID 40243407, 2025).
bladder (4 papers, 2011 to 2026). "Taking into account the promising results obtained, unveiling the putative biological relevance of miR663a and VIM promoter methylation in bladder carcinogenesis may provide new important insights." (PMID 32102337, 2020). "Histopathological examination confirmed IMT of the urinary bladder (IMTUB) with positive immunohistochemical staining for ALK, vimentin, and actin." (PMID 41827463, 2026). "During prostate carcinogenesis, EMT is related to cancer progression, migration and metastasis, and mesenchymal markers and transcription factors, such as vimentin, N-cadherin, Snai1, and Twist1/2, are highly upregulated." (PMID 34298624, 2021).
bone neoplasm (4 papers, 2021 to 2025). A benign, intermediate, or malignant neoplasm involving the bone or articular cartilage. "For bone tumors of mice injected with PT‐TNBCs, Slug, ALDH1, and vimentin expression was similarly reduced to 41.2% ± 14%, 33.0% ± 18%, and 54.0% ± 2.8%, respectively (n = 9, p < 0.001)." (PMID 35720668, 2022). "Rg3 also modulated EMT-related molecules, such as activations of E-cadherin and Snail and suppressions of N-cadherin, Vimentin, and zing-finger E-box-binding homeobox factor (ZEB) 1 in five different cell lines: lung, nasopharynx, colorectum, and bone tumor, respectively." (PMID 36012338, 2022). "Immunohistochemistry staining showed that miR-128 knockdown decreased expression of Wnt, β-catenin, E-cadherin, vimentin, and fibronectin, indicating that miR-128 knockdown inhibited the Wnt/β-catenin and EMT signaling pathways in tumor tissues of bone neoplasms." (PMID 33472642, 2021).
breast adenocarcinoma (4 papers, 2013 to 2020). "Ectopic stable IL-6 expressing MCF-7 breast adenocarcinoma cells exhibited an EMT phenotype characterized by impaired E-cadherin expression and induction of Vimentin, N-cadherin, Snail, and Twist." (PMID 30083161, 2018).
choroid plexus papilloma (4 papers, 2017 to 2022). "Immunohistochemical characteristics of choroid plexus papillomas are positive expressions of both cytokeratin and vimentin, while transthyretin and S-100 protein are expressed in 80% to 90% of choroid plexus carcinomas." (PMID 32756190, 2020). "Additionally, a mouse choroid plexus carcinoma cell line lacked expression of cytokeratin and Ecad and failed to establish junctional complexes, but was positive for vimentin and did not develop a barrier function." (PMID 36361697, 2022). "Examination of cytokeratin and vimentin pattern in choroid plexus papilloma (CPP) and atypical choroid plexus papilloma (ACPP) confirmed the absence of aggresomes in these two tumor subtypes." (PMID 28808307, 2017).
Crohn disease (4 papers, 2015 to 2021). A gastrointestinal disorder characterized by chronic inflammation involving all layers of the intestinal wall, noncaseating granulomas affecting the intestinal wall and regional lymph nodes, and transmural fibrosis. "The invasive properties of the cells of Crohn’s disease are linked to vimentin expression, as are inflammatory, bacterial, and signalling events." (PMID 30248895, 2018). "Moreover, vimentin-targeted treatment of Crohn’s-disease-associated Escherichia coli with withaferin-A promotes the correct functioning of the inflammatory response, autophagy, and cell invasion." (PMID 30248895, 2018). "Fibrotic areas show EMT-related markers, and particularly vimentin, which suggests that EMT is involved in the pathogenesis of Crohn’s disease." (PMID 30248895, 2018). "In addition, our human studies show that Wnt5a was clearly observed in vimentin-positive cells, but not macrophages, in the ulcer lesions of patients with ulcerative colitis and Crohn’s diseases." (PMID 26030277, 2015).
endocervical adenocarcinoma (4 papers, 2019 to 2024). An adenocarcinoma that arises from the endocervix. "Some, but not all, pathologists find CEA and vimentin to be of some value in the distinction of high-risk HPV-related endocervical adenocarcinomas from endometrial endometrioid adenocarcinomas 7–9." (PMID 30550485, 2019).
epilepsy (4 papers, 2021 to 2024). A brain disorder characterized by episodes of abnormally increased neuronal discharge resulting in transient episodes of sensory or motor neurological dysfunction, or psychic dysfunction. "According to the univariate analysis, 13 variables were significantly associated with survival: age, performance status, extent of surgery, tumor depth, tumor size, epilepsy, postoperative chemoradiotherapy, IDH mutations, CD44, HIF-1α, HIF-1β, vimentin, and PDFGR." (PMID 38927417, 2024). "In children, caspase-3 and S100 exhibit higher expression levels in patients with epilepsy, while GFAP and vimentin show minimal differences." (PMID 37833937, 2023). "Overall, the data suggests that caspase-3, S100, and vimentin exhibit differential expression patterns between epilepsy and non-epilepsy patients, while GFAP expression remains relatively consistent regardless of the condition." (PMID 37833937, 2023). "S100 expression is elevated in male epilepsy patients compared to those without epilepsy, whereas vimentin expression remains relatively low in both groups." (PMID 37833937, 2023). "For adults, the proteins caspase-3, S100, and vimentin show higher expression levels in patients with epilepsy compared to those without epilepsy, while GFAP shows a slight increase." (PMID 37833937, 2023). "S100 displays elevated expression in female epilepsy patients compared to those without epilepsy, while vimentin expression remains relatively low in both groups." (PMID 37833937, 2023).
germ cell tumor (4 papers, 2019 to 2025). A benign or malignant, gonadal or extragonadal neoplasm that originates from germ cells. "Vimentin and cytokeratin are expressed in many ovarian epithelial cell tumours, germ cell tumours and sex cord-stromal tumours, although with variable degrees of immunoreactivity." (PMID 31547830, 2019). "The initial biopsy indicated a germ cell tumor with yolk sac based on these immunohistochemical markers: SALL-4, cytokeratin, and vimentin." (PMID 40225550, 2025). "Immunohistology showed positive stainings of vimentin, calretinin, and inhibin with negative stainings of the typical germ cell tumor markers." (PMID 31236304, 2019).
giant axonal neuropathy (4 papers, 2017 to 2022). A rare inherited disorder affecting the neurofilaments. "Increased accumulation of vimentin was reported in giant axonal neuropathy (GAN), which is caused by mutations of GAN gene encoding for a member of E3 ubiquitin ligases." (PMID 30397214, 2018). "Vimentin aggregates are found in pathological situations such as cataract induced by mutant vimentin, giant axonal neuropathy, or glyoxal-treated skin fibroblasts." (PMID 31480524, 2019). "Most recently, vimentin aggregates were shown to inhibit trafficking of mitochondria in giant axonal neuropathy strengthening the hypothesis that reduced phosphorylation of intermediate filaments leads to a trafficking defect in neurodegenerative disease." (PMID 28841900, 2017).
granulosa cell tumor (4 papers, 2012 to 2025). A slow-growing, malignant tumor, characterize by the presence of granulosa-like cells and Call-Exner bodies, that is almost always found in the ovary. "Immunohistochemistry analysis was positive for FOXL2, inhibin, and vimentin, confirming adult granulosa cell tumor classified as International Federation of Gynecology and Obstetrics IC1." (PMID 41137270, 2025). "Luteinized granulosa cell tumor shows varying presence of nuclear grooves with vimentin, inhibin, calretinin, CD99, and SMA positivity with variable immunoreactivity for desmin and PanCK and negativity with EMA." (PMID 27818820, 2016). "In particular all juvenile granulosa cell tumors were Inhibin and Vimentin positive, whereas Pancytokeratin was focally positive in 50% (3/6)." (PMID 23029311, 2012).